PLAT (plasminogen activator, tissue type)
Description:
Converts the abundant, but inactive, zymogen plasminogen to plasmin by hydrolyzing a single Arg-Val bond in plasminogen. By controlling plasmin-mediated proteolysis, it plays an important role in tissue remodeling and degradation, in cell migration and many other physiopathological events. During oocyte activation, plays a role in cortical granule reaction in the zona reaction, which contributes to the block to polyspermy (By similarity).
Synonyms: t-PA; tPA
Tractability: Small molecule: an approved drug acts on it; a structure with a bound ligand is known; a high-quality ligand is known; it has a binding pocket of medium quality; it belongs to a druggable protein family. Antibody: its Gene Ontology location is reachable by antibodies, with high confidence; UniProt places it where antibodies can reach, with medium confidence; UniProt predicts a signal peptide or a membrane-spanning region. PROTAC: its protein half-life has been measured; a small molecule that binds it is known. Other modalities: an approved drug acts on it.
Target class: Serine protease; Enzyme; Serine protease PA clan; Serine protease S1A subfamily; Protease
Gene: Protein-coding gene on chromosome 8 (42,174,718 to 42,207,709, reverse strand). Ensembl gene ENSG00000104368.
Subcellular location: Secreted, extracellular space
Subcellular location (Human Protein Atlas): Actin filaments; Predicted to be secreted
Pathways (Reactome):
Hemostasis: Dissolution of Fibrin Clot
Signal Transduction: Signaling by PDGF
Gene Ontology:
Molecular function: phosphoprotein binding; protein binding; serine-type endopeptidase activity; signaling receptor binding
Biological process: negative regulation of proteolysis; plasminogen activation; blood coagulation; fibrinolysis; negative regulation of fibrinolysis; negative regulation of plasminogen activation; platelet-derived growth factor receptor signaling pathway; prevention of polyspermy; protein modification process; proteolysis; smooth muscle cell migration; trans-synaptic signaling by BDNF, modulating synaptic transmission; zymogen activation
Cellular component: cell surface; cytoplasm; extracellular exosome; extracellular matrix; serine protease inhibitor complex; extracellular region; apical part of cell; glutamatergic synapse; Schaffer collateral - CA1 synapse; secretory granule
Genetic constraint (gnomAD): Loss-of-function variants: 34 observed, 56.3 expected, observed/expected ratio (o/e) 0.6, 90% interval 0.46 to 0.8. The upper end of that interval is the gene's LOEUF score, 0.8, which puts it in group 3 of 6, group 1 being the genes least tolerant of losing a copy. Missense variants: 549 observed, 615.35 expected, observed/expected ratio (o/e) 0.89, 90% interval 0.83 to 0.96. Synonymous variants: 262 observed, 253.63 expected, observed/expected ratio (o/e) 1.03, 90% interval 0.93 to 1.14.
Homologues: Orthologues: chimpanzee PLAT (99% identical), macaque PLAT (98% identical), guinea pig PLAT (81% identical), rat Plat (81% identical), pig PLAT (81% identical), dog PLAT (81% identical), mouse Plat (80% identical), rabbit PLAT (67% identical), tropical clawed frog plat (55% identical), zebrafish plat (54% identical). Paralogues in human: PLG (31% identical), OVCH1 (17% identical), PRSS33 (17% identical), PRSS48 (16% identical), TMPRSS12 (16% identical), PRSS27 (15% identical), KLK15 (15% identical), PRSS50 (14% identical), KLK9 (14% identical), PRSS57 (14% identical), GZMM (13% identical), PRSS37 (11% identical), and 2 more.
Diseases named in the same sentence as PLAT in open-access papers:
PLAT is named in the same sentence as 383 diseases in open-access papers, as found by Europe PMC text mining. Sharing a sentence is not in itself a finding about the gene and the disease. The quoted sentences say what the papers report.
Stroke (788 papers, 2004 to 2026). Sudden impairment of blood flow to a part of the brain due to occlusion or rupture of an artery to the brain. "Polymorphisms in tissue-type plasminogen activator encoded by PLAT are implicated in strokes and myocardial infarctions and susceptible to bacterial osteomyelitis." (PMID 34456633, 2021). "If the effect of the Alu polymorphism was as predicted by previous studies, we expect to see individuals with the PLAT Alu DD genotype at a higher risk for developing diseases of hypercoagulative nature, such as pulmonary embolism (PE), venous thromboembolism, myocardial infarction, and stroke." (PMID 33390179, 2021). "In the comparison of the controls against each patient group including “random,” “stroke,” and “long survivor” groups, we found PLAT and SLC19A2 [MIM: 603941] to be consistently significant in gene‐specific differences in allele frequencies across all the comparisons." (PMID 32898326, 2020).
ischemic stroke (437 papers, 2006 to 2026). A stroke disorder caused by obstruction of blood flow to the brain, due to thrombotic (local blood clot formation) or embolic (due to a blood clot or other material traveling from another site) event. "In addition, it is interesting to note that intravascular injection of recombinant PLAT is used in clinics to induce thrombolysis in ischemic stroke." (PMID 36497184, 2022).
COVID-19 (110 papers, 2020 to 2025). A disease caused by infection with severe acute respiratory syndrome coronavirus 2. "Overall, these results suggest that CALCA, TNF, and PLAT are strongly associated with COVID-19, while PPARG has a relatively weaker association." (PMID 40766923, 2025). "We reviewed studies surrounding polymorphic Alu retrotransposons in ACE, PGR, PLAT, and F13B that have been either mechanistically linked to and/or associated with clinical conditions relevant to COVID-19." (PMID 33390179, 2021). "Here, we briefly summarize and examine known Alu polymorphisms in ACE, PGR, PLAT, F13B regarding their biological functions, roles in disease, and implications for COVID-19." (PMID 33390179, 2021). "Nevertheless, given the importance of the coagulation/fibrinolysis system in the pathogenesis of COVID-19, the function of the Alu variant of the PLAT gene cannot be ignored in future studies." (PMID 34680966, 2021). "Similar to the ACE and PLAT Alu I/D polymorphism, the F13B variation observed across the human population could be an important biological factor when considering the variable individual response to COVID-19." (PMID 33390179, 2021). "As plasminogen and plasmin can serve as a complement inhibitor and C5 convertase, respectively, the PLAT Alu I/D could also affect complement activation in COVID-19." (PMID 33390179, 2021). "Using gene network analysis, a prior study identified PLAT as a SARS-CoV-2 target and elucidated its potential involvement in COVID-19’s inflammatory response, metabolism of reactive oxygen species, and immune response." (PMID 37251077, 2023). "Detailed in vivo and in vitro studies will be required to better understand the viral-host dynamics with respect to T-PA (PLAT) and PAFR (PTAFR) activation and the subsequent systemic inflammatory responses, in symptomatic and asymptomatic COVID-19 populations." (PMID 34786557, 2020). "The PLAT gene could be a possible hub that links hyperglycemia, COVID-19, and negative cardiovascular events." (PMID 35806251, 2022).
myocardial infarction (86 papers, 2006 to 2025). Gross necrosis of the myocardium, as a result of interruption of the blood supply to the area, as in coronary thrombosis. "Other processes in which hypofibrinolysis is a contributing disease mechanism, such as myocardial infarction and lacunar stroke, have also been associated with the T allele of the PLAT -7351 C/T SNP and these two diseases are observed at increased rate in RA." (PMID 16356191, 2006).
diabetes (63 papers, 2009 to 2026). "Elevated expression of PLAT has been linked to endothelial dysfunction and a heightened risk of thrombotic events, consistent with the vascular complications frequently observed in patients with uncontrolled diabetes." (PMID 40458179, 2025). "The upregulation of genes such as PLAT (plasminogen activator) in the T2DMpoorly-DLP-H group reflects the increased fibrinolytic activity and vascular inflammation associated with poorly managed diabetes." (PMID 40458179, 2025).
thrombosis (54 papers, 2006 to 2025). "Here, we reported a newly identified rare homozygous point mutation c.1411T>C (p.Y471H) in the PLAT gene, which led to the mutation of amino acid 471 of tPA from tyrosine (Tyr) to histidine (His), and the proband carrying the mutation suffered from deep vein thrombosis." (PMID 37808270, 2023).
endothelial dysfunction (45 papers, 2009 to 2025). In vascular diseases, endothelial dysfunction is a systemic pathological state of the endothelium (the inner lining of blood vessels) and can be broadly defined as an imbalance between vasodilating and vasoconstricting substances produced by (or acting on) the endothelium. "The prothrombotic shift in infected lungs was revealed by increased expression of the coagulation cascade mediators TF, PLAT, PAI-1, THBD, and vWF associated with endothelial dysfunction as shown through the upregulated expression of ESAM, CD106, CD201, VEGF-A, and VEGFR-2." (PMID 38474396, 2024).
breast carcinoma (36 papers, 1990 to 2025). "For gene markers in HER2 breast cancers, possible targeting of individual clusters with PLAT, ICAM1, and FGA is observed." (PMID 36598637, 2023). "PLAT has been identified as an immune checkpoint gene that exerts a critical influence on the prognosis of various cancers, such as breast cancer and hepatocellular carcinoma, by modulating the levels of immune molecules and regulating the infiltration of immune cells in the tumor microenvironment." (PMID 37251077, 2023). "Literature reports indicate that 15.6% of breast cancer tumors present PLAT amplification." (PMID 34746770, 2021). "Reports in the literature point out the amplification of PLAT in breast cancer." (PMID 34746770, 2021). "Basal-B lines were characterized by markers associated with aggressive tumor features, including PLAT (plasminogen activator) and TGFB1, as well as marker phenotypes associated with normal breast and breast cancer progenitor/stem cells (MUC−/CALLA+; CD44+/CD24−/low; and ITGB3(CD61)+)." (PMID 19582160, 2009). "There were 76 proteins detected only in the AQP1-overexpressing group, including proteins reported to exert prosurvival and/or prometastatic activities in breast cancer, such as intercellular adhesion molecule 1 (ICAM1), cathepsin S (CTSS), and PLAT." (PMID 36803413, 2023). "Some genes contribute a lot to the riskscore, however, their roles in breast cancer were largely unstudied, for instance, Peroxidasin like (PXDNL), ATPase phospholipid transporting 8A2 (ATP8A2) and plasminogen activator, tissue type (PLAT)." (PMID 35443644, 2022). "Considering that PLAT was reported to promote tumor angiogenesis in lung cancer but low expression of PLAT indicates poor prognosis in breast cancer, wound healing assay and HUVEC tube formation assay were carried out to validate the relationship between angiogenesis and PLAT in thyroid cancer." (PMID 38186223, 2024). "For example, CST1 is highly expressed in Luminal B breast cancer cells, SEMA3B is highly expressed in HER2-positive breast cancer cells, while SEMA3B stands out in the analysis of progression-free survival, and PLAT is highly expressed in basal-like breast cancer cells." (PMID 39493752, 2024). "Interestingly, PLAT is never expressed in patients with breast cancer classified as TNBC." (PMID 34746770, 2021).
atherosclerosis (33 papers, 2007 to 2025). A disease characterized by the build-up of fatty material and calcium deposition in the arterial wall resulting in partial or complete occlusion of the arterial lumen. "Because PLAT and PLAU are also associated with atherosclerosis/thrombotic pathways and JAKinib therapy was associated with MACE, we focused on these transcripts for further analyses." (PMID 40522928, 2025). "Because PLAT and PLAU are also associated with atherosclerosis/thrombotic pathways and JAKinib therapy is associated with MACE, we focused on these PLAT and PLAU transcripts for further analyses." (PMID 39386576, 2025).
coronary heart disease (31 papers, 2007 to 2025). "Six genes (ABCB1, PLAT, ACE, GH1, PECAM1, and RGS9) known to predispose people to coronary artery disease occur in the cn-LOH regions identified." (PMID 28120895, 2017). "Changes in plasminogen activator inhibitor 1 and tissue-type plasminogen activator (PLAT gene) were detected during exercise in patients with coronary artery disease." (PMID 22761820, 2012).
hypercoagulability (21 papers, 2011 to 2025). "However, in the context of thrombophilia, pathogenetic mutations in PLAT have rarely been reported." (PMID 37808270, 2023). "Gene sequencing revealed that the proband had a homozygous c.1411T>C (p.Y471H) mutation of PLAT, without common severe thrombophilias such as protein C, protein S, or antithrombin deficiency." (PMID 37808270, 2023).
Obesity (17 papers, 2009 to 2026). Accumulation of substantial excess body fat. "These molecular alterations demonstrate that vascular risk in childhood obesity begins at the transcriptomic level long before clinical symptoms emerge, highlighting the ATF6/PLAT axis as a potential biomarker for early risk assessment." (PMID 41898467, 2026). "In conclusion, the suppression of ATF6 in obesity indicates the "exhaustion" of adaptive cellular defense mechanisms, while the upregulation of PLAT points to a compensatory response to the chronic prothrombotic environment." (PMID 41898467, 2026). "Importantly, plasma tPA was reduced in the hepatocyte–PAI-1 KO obese mice, indicating that the PAI-1/PLAT pathway is an important contributor to the increase in hepatocyte-derived plasma tPA in obesity." (PMID 32657780, 2020). "We focused on the PAI-1/PLAT pathway, which mitigates the reduction in fibrinolysis in obesity." (PMID 32657780, 2020). "Together, these data provide support for a pathway in which the increase in hepatocyte PAI-1 in obesity, mediated at least in part by suppression of Rev-Erbα, activates an LRP1/PKA/p-CREB/PLAT pathway that lessens the magnitude of the PAI-1–mediated decrease in fibrinolysis in obesity." (PMID 32657780, 2020).
melanoma (16 papers, 1999 to 2025). A malignant, usually aggressive tumor composed of atypical, neoplastic melanocytes. "In Bowes melanoma cells, the PLAT promoter and the MHRE were fully unmethylated and t-PA secretion was extremely high." (PMID 27973546, 2016). "PIK3R5 and PLAT positively regulated cancer metastasis and EMT of osteosarcoma cells and melanoma, respectively, while little is known about their roles in EOC metastasis." (PMID 35538537, 2022). "Specifically, FLRT2 was downregulated while MAD1L1, PHLDA2, PLAT, CC2D1B, CDKN2A and RUNX3 were upregulated in both melanoma and in Group 2 and Group 3 SFs." (PMID 23371019, 2013). "Note the extremely high secretion rate of t-PA from and t-PA mRNA levels in Bowes melanoma cells and the complete absence of CpG methylation in the PLAT promoter region and near the MHRE with these cells." (PMID 27973546, 2016). "Before studying the influence of PLAT gene promoter/enhancer methylation on PLAT gene expression, we investigated the PLAT transcriptional start site (TSS) by 5’RACE analysis using total RNA from five t-PA expressing cell types: astrocytes, Bowes melanoma cells, HeLa cells, HUVEC and HT1080 cells." (PMID 27973546, 2016).
coagulopathy (15 papers, 2016 to 2026). "The P‐selection and vWF were expressed in the initial phase of coagulopathy, unlike the PLAT, PAI‐1, and TF, which were upregulated in the late phase (fibrinolytic system)." (PMID 38098255, 2024).
Anxiety (13 papers, 2007 to 2025). Intense feelings of nervousness, tension, or panic often arise in response to interpersonal stresses. "Conditional deletion of PLAT in the central amygdala leads to locomotor hyperactivity and reduced anxiety." (PMID 40766923, 2025). "The meta-analysis confirmed increased expression of four anxiety-related molecular mediators in response to COVID-19 infection: CALCA, TNF, PLAT, and PPARG, with the latter three associated with neurocognitive decline." (PMID 40766923, 2025). "PLAT mediates stress-induced anxiety by promoting neuronal activity in the medial amygdala and the rapid outgrowth of presynaptic connections." (PMID 40766923, 2025). "The enzyme tissue plasminogen activator (PLAT) is involved in various brain functions involving behavior and emotions, including fear/anxiety in the amygdala and plays a crucial role in regulating anxiety and fear responses in the amygdala, as evidenced by several studies." (PMID 40766923, 2025). "Specifically, SARS-CoV-2 infection appears to upregulate multiple pro-inflammatory cytokines and secreted proteins (e.g., CALCA, TNF, PLAT, PPARG), which are known to promote anxiety phenotypes, while anxiety itself may modulate key regulators of viral pathophysiology." (PMID 40766923, 2025).
glioma (13 papers, 1989 to 2025). A benign or malignant brain and spinal cord tumor that arises from glial cells (astrocytes, oligodendrocytes, ependymal cells). "(2024) identified a negative correlation between PLAT expression, a venous thromboembolism-associated gene upregulated in gliomas, and ouabain sensitivity, suggesting that tumors with high PLAT levels may be more susceptible to ouabain’s cytotoxic effects." (PMID 41280918, 2025). "Analysis of the associative relationships ofindividual representatives of the selected pairs revealed that the level ofmRNAs encoded by the ELN, ARL4C,C9orf64, PLAT, and FKBP9genes associated with aggressive progression of glioma was increasedin the IDHwt group." (PMID 39539523, 2024). "PLAT encodes a serine protease that activates plasminogen to plasmin and has been identified as a key gene associated with immune infiltration in lower-grade gliomas." (PMID 38955935, 2024). "While these four genes (PDGFA, PDGFRA, CREB1, and PLAT) have been studied individually, our findings highlight their collective significance in glioma." (PMID 39606019, 2024). "Our analysis revealed a positive correlation between VRG expression and DNAss in specific cancers, particularly, F3, PLAT, and C1S and DNAss in glioblastoma and lower grade glioma (GBMLGG), suggesting a potential role of these genes in promoting tumor stemness in these specific cancers." (PMID 39179711, 2024). "No data on the involvement of such genesas ASCC1, ZCCHC17 (participates in biogenesisof ribosomal DNA), PLAT, CISD1,TMEM229a and RANBP3L in the development and spread ofany glioma types have been found." (PMID 39539523, 2024). "The violin plot demonstrated that IGFBP2, SMC4, PLAT, and ANXA1, showed relatively higher expression levels in pericytes and glioma cells compared to other scoring genes." (PMID 39906742, 2024). "The 89-gene signature consists of a number of hypoxia and inflammation-related genes such as AKR1C3, PTX3, PLAT and IGFBP2, showing that these two inseparable hallmarks are involved in tumor progression and play significant roles in glioma pathogenesis." (PMID 27323413, 2016). "Pathway enrichment analysis identified four essential genes—PDGFA (ligand), PDGFRA (receptor), CREB1 (TF), and PLAT (target gene)—involved in the Receptor Tyrosine Kinases (RTK) signaling pathway, which plays a pivotal role in glioma progression from grade III to grade IV." (PMID 39606019, 2024).
Insulin resistance (12 papers, 2012 to 2025). Increased resistance towards insulin, that is, diminished effectiveness of insulin in reducing blood glucose levels. "protein C receptor, endothelial (EPCR) (PROCR), C1R, CFI, PLAT, C4BPB, and CFB are novel biomarkers for the development of insulin resistance." (PMID 30678306, 2019).